SMARCA4 (SWI/SNF related BAF chromatin remodeling complex subunit ATPase 4)
Diseases named in the same sentence as SMARCA4 in open-access papers (continued):
Sharing a sentence is not in itself a finding about the gene and the disease.
tumor (558 papers, 2005 to 2026). "SMARCA4 mutations are prevalent in various cancers, including lung, gastric, and breast carcinomas, and are associated with aggressive tumor behavior and poor outcomes." (PMID 41577374, 2026). "It recruits an E3 ligase to induce highly selective (>1000‐fold) degradation of SMARCA2 and demonstrates anti‐proliferative activity against SMARCA4‐deficient tumours in vitro and in vivo with good tolerability." (PMID 41537447, 2026). "We report the first comprehensively molecularly characterized case of a peri-implant gingival SWI/SNF complex-deficient tumor with confirmed biallelic SMARCA4 inactivation." (PMID 42279597, 2026). "SMD‐3040 is a highly efficient and selective SMARCA2 degrader (>80‐fold selectivity) with preferential activity in SMARCA4‐deficient tumour cells." (PMID 41537447, 2026). "Co‐occurring mutations with smoking‐related canonical mutations, such as KRAS, STK11, and KEAP1, are common in patients with SMARCA4 mutations, and up to 44% of these patients exhibit a smoking‐related co‐mutation signature and a high tumor mutational burden." (PMID 41577374, 2026). "delineated divergent prognostic associations: SMARCA4 overexpression correlates with tumour invasiveness, whereas elevated SMARCA2 expression marks benign differentiation states—a dichotomy particularly pronounced in HCC." (PMID 41578412, 2026). "Thoracic SMARCA4‐deficient undifferentiated tumors (SMARCA4‐UT) are rare, aggressive neoplasms that have recently been recognized as a distinct entity." (PMID 41577374, 2026). "The tumor, in our case, arose in the abdominal organs and appears to share a similar oncogenic process with the category of thoracic SMARCA4-deficient undifferentiated tumors in the WHO classification." (PMID 40012963, 2025). "Several prognostic factors have been identified, including the stage of disease at diagnosis, the volume of residual tumor after cytoreductive surgery, the SMARCA4 mutation status, and the presence of hypercalcemia." (PMID 40896427, 2025). "Histologically, SMARCA4-deficient tumors present as infiltrative, diffuse sheets of undifferentiated cells, frequently accompanied by variable rhabdomyoblastic tumor cell components." (PMID 41312169, 2025). "Prior to this review, most published data on SMARCA4-altered malignancies were limited to isolated case reports or small tumor-specific series, particularly those focusing on thoracic SMARCA4-deficient undifferentiated tumors (SMARCA4-UT)." (PMID 40867304, 2025). "Diagnosis of the tumor and discovery of the novel SMARCA4 variant was only possible after comprehensive tumor molecular testing tailored for pediatric malignancies." (PMID 40036664, 2025). "Inhibition of PD-L1 and TIGIT through atezolizumab and tiragolumab, respectively, is being examined in a phase I/II clinical trial for the treatment of relapsed or refractory SMARCB1- or SMARCA4-deficient tumours." (PMID 40422882, 2025). "Together, these findings establish SMARCA4 loss as a key driver of NE differentiation in KC1 tumours." (PMID 41025426, 2025). "Pathological analysis confirmed the malignancy of the tumor, and based on the immunophenotype, it was classified as a SMARCA4-deficient undifferentiated tumor." (PMID 41142791, 2025). "Our case of SMARCA4-UT exhibiting a high tumor mutational burden demonstrated a favorable response to the immunotherapy (tislelizumab) combined with chemotherapy and radiotherapy." (PMID 41261718, 2025). "Histopathologically, in NSCLC (frequently LUAD), NE markers have been observed in tumours deficient in SMARCA4, SMARCA2 and even SMARCB1." (PMID 41025426, 2025). "The neoplasm demonstrated regional loss of SMARCA4 in areas where neuroendocrine markers were positive." (PMID 39888726, 2025). "The absence of Claudin-4 expression further supported the diagnosis of a mesenteric SMARCA2-deficient yet SMARCA4-preserved undifferentiated tumor." (PMID 40012963, 2025).
tumor (continued). "NGS also detected a heterozygous missense variant in SMARCA4 (c.3484G > A, p.Gly1162Ser) in the tumor DNA with a VAF of 56%, affecting the C-terminal helicase domain of the protein." (PMID 41168858, 2025). "Here, we describe a rare case of a SMARCA4-deficient tumor originating in the tonsil with widespread metastasis at presentation and a notable complete response to chemoimmunotherapy." (PMID 40978837, 2025). "Clinically, the progression of SMARCA4-deficient tumors occurs at a significantly faster rate compared to other tumor types." (PMID 41312169, 2025). "Significant histopathological diversity with inflammatory infiltration and tumor necrosis characterizes SMARCA4-deficient NSCLC." (PMID 39888726, 2025). "STK11, KEAP1, and SMARCA4 are tumor suppressors in lung tissue and mutations in those genes correlate with significantly worse outcomes for patients with NSCLC, particularly after ICI therapy." (PMID 41387924, 2025). "Subsequent 18F-FDG PET/CT resolved this challenge by identifying hypermetabolic foci (SUVmax 8.5) within the lesion, guiding a repeat biopsy to viable tumor regions that confirmed SMARCA4 loss (BRG1-negative, Ki67 70%)." (PMID 40978036, 2025). "Sporadic ATRTs are notable for their aggressive behavior and poor prognosis, particularly associated with mutations in the SMARCB1 or SMARCA4 tumor suppressor genes, leading to unchecked cellular proliferation and tumor development." (PMID 41155355, 2025). "For example, mutations in SWI/SNF complex subunits, including ARID1A or SMARCA4, are prevalent in a variety of tumor types and enhance the tumor’s epigenetic flexibility and adaptability." (PMID 41155227, 2025). "Thoracic SMARCA4-deficient undifferentiated tumor (SMARCA4-UT) is an aggressive tumor with a dismal prognosis, most commonly involving the mediastinum and lungs." (PMID 40406754, 2025). "Our results highlight the biological complexity of SMARCA4 class 1 versus class 2 mutations and their role in tumor progression when co-mutated with KRAS in patients with NSCLC." (PMID 41007704, 2025). "The loss of SMARCA4 is associated with the development of advanced dedifferentiated tumors and an increased incidence of tumor metastasis.The SMARCA4 gene encodes the BRG1 protein, and its loss is associated with a poor prognosis." (PMID 41142791, 2025). "Tuvusertib/niraparib combo-therapy demonstrated greater anti-tumor activity than tuvusertib monotherapy in SMARCA4-deficient LUAD xenograft models." (PMID 39875375, 2025). "In GC, missense mutations in SMARCA4 can impair its tumor‐suppressive function, potentially leading to more aggressive GC." (PMID 40926327, 2025). "This case highlights the potential of a mechanistic-driven, multimodal strategy to overcome therapeutic resistance in SMARCA4-deficient undifferentiated tumor." (PMID 40978036, 2025). "A Mutation in the SMARCA4 gene (BRG1) induces genomic instability and high tumor mutational burden (TMB), promoting neoantigen expression amenable to immune checkpoint inhibitors." (PMID 40978036, 2025). "The thorax was the most common primary tumor site (n = 59, 40.0%), encompassing both thoracic SMARCA4-deficient undifferentiated tumors (SMARCA4-UT) and SMARCA4-altered non-small cell lung cancers (NSCLC)." (PMID 40867304, 2025). "These included both single case reports and small case series of SMARCA4-mutated or SMARCA4-deficient malignancies, encompassing diverse tumor types, clinical presentations, and therapeutic strategies." (PMID 40867304, 2025). "As a tumor suppressor, SMARCA4 mutations and low expression are associated with a poor prognosis in various cancers." (PMID 39322625, 2024).
tumor (continued). "SMARCA4‐deficient undifferentiated tumor (SMARCA4‐UT) in the chest is a high‐grade malignant tumor that grows rapidly and often carries a poor prognosis." (PMID 39648153, 2024). "The chromatin remodeler SMARCA4, for instance, has been validated as a tumor suppressor, with its diminished expression linked to enhanced colorectal cancer metastasis via the Wnt/β‐catenin signaling pathway." (PMID 38374872, 2024). "This genetic alteration is particularly associated with several aggressive tumor types, including small cell carcinoma of the ovary, and the SMARCA4-UT." (PMID 39360100, 2024). "With SMARCA4-deficient tumor cell selectivity, it can effectively inhibit the growth of SAMRCA4-deficient tumors and is well tolerated." (PMID 39697230, 2024). "All four specimens showed complete loss of SMARCA4 (BRG1) in the tumor nuclei, with endothelial and inflammatory cells as internal positive controls, and showed negative expression of epithelial markers, including PCK, EMA and/or CK7." (PMID 38877473, 2024). "Regarding tumor location, in the SMARCA4-mutated group, eight (42.1%) tumors were located in the esophagus, five (26.3%) at the esophagogastric junction, and six (31.6%) in the stomach." (PMID 38610978, 2024). "In SMARCA4-deficient tumor cells, the activity of AURKA is necessary for mitotic spindle assembly and cell survival, and it has been demonstrated that the AURKA inhibitor (VX-680) induces tumror cells death in vitro and in mouse vivo assays." (PMID 38347129, 2024). "Testing for SMARCA4 (BRG-1) by IHC showed a complete loss in the tumor cells, favoring the diagnosis of Thoracic SMARCA4-deficient undifferentiated tumor (SMARCA4-UT)." (PMID 38265099, 2024). "Our case adds to the limited other reports of successful SMARCA4-deficient tumor diagnosis using EBUS-TBNA alone." (PMID 39886719, 2024). "It is possible that the loss of SMARCA4 in SCCOHT reprograms the transcriptional landscape to influence tumour immunogenicity, creating an environment that is more permissive to ICB." (PMID 39272926, 2024). "In order to improve the diagnosis and prognosis of patients with SMARCA4-UT, this article reviewed the diagnostic and therapeutic strategies, particularly immunotherapy, tumor microenvironment (TME), epigenetic regulation and novel targeted therapy." (PMID 38347129, 2024). "SMARCA4-deficient tumors are a group of aggressive neoplasms characterized by the inactivation of the SMARCA4 gene, a key component of the SWI/SNF chromatin remodeling complex." (PMID 39199375, 2024). "Studies have shown that SMARCA4 deficiency increases the infiltration of anti‐tumor immune cells, thereby improving the response to immunotherapy." (PMID 39322625, 2024). "SMARCA4 mutations and low expression were associated with shorter survival, and mutations were associated with a high tumor mutational burden and high microsatellite instability." (PMID 39322625, 2024). "This would indicate that at least in these tumours, SMARCA4 mutation is occurring as an early event across the timeline of tumorigenesis." (PMID 39272926, 2024). "On one hand, several reports showed the promising antitumor activity of ICIs against this type of tumor, on the other hand, others reported the dessert immune microenvironment of SMARCA4‐deficient tumors with limited efficacy to ICIs." (PMID 38923369, 2024). "The potential ineffectiveness of ICI treatment in NSCLC is explored through the impact of SMARCA4/KRAS co-mutations on the tumor microenvironment." (PMID 39063938, 2024). "Various studies have noted an association between SMARCA4 mutations and an increase in tumor-infiltrating immune cells, as well as T cell function." (PMID 38610978, 2024). "These tumors are rare, aggressive neoplasms, characterized by the loss of protein product of SMARCA4 (Brahma-related gene-1) and the preservation of INI1 (SMARCB1) expression." (PMID 38497146, 2024).
tumor (continued). "The specimen obtained by CT-guided biopsy showed the proliferation of homogeneous tumor cells with weak cohesiveness and a complete loss of SMARCA4 expression on immunohistochemical examination." (PMID 39497014, 2024). "This suggests that the tumor probably began developing several months earlier and is relevant to the literature data that SMARCA4 gene-associated cases occur at a young age." (PMID 40729139, 2024). "Particularly, immunotherapies targeting neoantigens from oncogenic driver mutations such as CTNNB1, DDX3X, and SMARCA4 and TAAs which have possible implications in tumor progression such as NEUROG1 and PIK3R3 are attractive for a better outcome in patients." (PMID 39160595, 2024). "In association with SMARCA4 mutations and clinico-genomic biomarkers across two different studies, tumor mutational burden (TMB) and brain metastasis in Anaplastic Lymphoma Kinase (ALK)-positive NSCLC were evaluated." (PMID 39063938, 2024). "We obtained the patient’s sister’s tumor tissue, and Sanger sequencing confirmed the presence of the same SMARCA4 pathogenic variant in her tissue sample." (PMID 39439958, 2024). "Here, we present the case of a patient with a stage II tumor who underwent surgical intervention, and we discuss the diagnosis and treatment of SMARCA4-deficient undifferentiated lung tumors." (PMID 38903719, 2024). "In this present case, the histological morphology of the rhabdoid‐like undifferentiated tumor led us to suspect a SWI/SNF‐deficient tumor, and subsequent immunostaining led to the diagnosis of a SMARCA4‐deficient undifferentiated tumor." (PMID 38923369, 2024). "We have found that male patients had substantially worse prognosis than female patients whose tumor carried a SMARCA4 mutation." (PMID 37345003, 2023). "SMARCA4‐dNSCLC was significantly associated with older age, male sex, smoking history, larger invasive tumor size, higher tumor proliferation index (Ki‐67), more adrenal metastases, more lymph node metastases, and few EGFR mutations (p < 0.05)." (PMID 37184108, 2023). "SMARCA4 is one of the most frequently mutated chromatin remodeling ATPases in cancer, and it manifests itself in a highly tumor-specific and tissue-specific manner." (PMID 36902184, 2023). "SMARCA4 is mutated in around 26% of all WNT tumours and 11% of all Group 3 tumours, with some studies identifying SMARCA4 as the most frequently mutated gene in Group 3 tumours." (PMID 37433987, 2023). "Although, in many tumor types, SMARCA4 displays loss-of-function mutations characteristic of a tumor suppressor, an additional role as a tumor-supportive gene in certain malignancies is emerging." (PMID 36810086, 2023). "A thoracic SMARCA4-deficient undifferentiated tumor (also known as a SMARCA4-deficient thoracic sarcoma) is a newly identified SMARCA-deficient neoplasm with an ICD-O code." (PMID 36178285, 2023). "Loss of SMARCA4 leads to the occurrence of advanced dedifferentiated tumors and increases the incidence of tumor metastasis." (PMID 37184108, 2023). "One of the most striking differences is that the tumor size of SMARCA4-UT is significantly larger than that of SMARCA4-deficient NSCLC." (PMID 37115343, 2023). "Renamed as “SMARCA4‐deficient undifferentiated tumor,” this tumor type distinctly differs from SMARCA4‐deficient NSCLC in phenotype." (PMID 38124509, 2023). "In these cancers, SMARCA4 has a tumour-supressing quality and mutation is thought to contribute to cancer development." (PMID 37433987, 2023). "Taken together, these findings provide evidence for a tumor-promoting role of a SMARCA4 deficiency in Group 3 MB." (PMID 37919824, 2023). "In spite of the inactivating mutation, immunohistochemistry showed diffuse SMARCA4 positivity (although with variable intensities) in virtually 100% of cells of the primary tumor." (PMID 38201285, 2023). "SMARCA4-deficient undifferentiated uterine sarcoma (SDUS) is a highly invasive single-gene malignant tumor caused by mutations in the SMARCA4 gene." (PMID 37194064, 2023).
tumor (continued). "Previous studies have shown that SCCOHT is a diploid tumor with a high probability of harboring SMARCA4 mutation." (PMID 37535222, 2023). "Homozygous deletion of SMARCA4 causes embryonic lethality at peri-implantation stage while its heterozygous deletion causes increased risk of neoplasia." (PMID 37345003, 2023). "Numerous studies have suggested that SMARCA4 is involved in tumorigenesis as a tumor suppressor, mainly through its loss-of-function mutations." (PMID 36902184, 2023). "The majority of these mutations have only been reported in a single patient as SMARCA4-deficient tumours make up a small subset of ATRT cases, yet they share characteristics such as location and mutation type." (PMID 37433987, 2023). "The tumor mutation burden of SMARCA4-UT was comparable to that of SMARCA4-deficient NSCLC (14.2 and 15.8 mutations per megabase, respectively)." (PMID 37115343, 2023). "Homozygous nonsense SMARCA4 mutations also in the ATPase domain are most frequently observed in ATRT tumours which retain SMARCB1 expression." (PMID 37433987, 2023). "Meanwhile, Sanger validation demonstrated that SCCOHT-CH-1 harbored two SMARCA4 mutations (c.939_940insT and c.2631C > A) which were identical to the patient’s tumor tissue." (PMID 37535222, 2023). "Immunohistochemical analysis showed diffused SMARCA4 expression in the primary tumor but almost complete loss of expression in TCS627 cells, while p16 showed nuclear positivity both in the primary tumor and TCS627 cells." (PMID 38201285, 2023). "Based on the morphological and immunohistochemical features, the tumor was diagnosed as GI NEC with SMARCA4 deficiency." (PMID 38090508, 2023). "A SMARCA4 splicing mutation, c.355 + 190_616del, was detected at a MAF of 86.4% in the tumor sample, accompanied by a SMARCA4 frameshift mutation p.H571Gfs (45.8%)." (PMID 37194064, 2023). "Whilst this is a small proportion (n = 3) of total ATRT-SHH tumours (n = 65), SMARCA4 mutation does occur at a much lower rate compared to SMARCB1 in ATRT and its exclusivity to the SHH subgroup is notable." (PMID 37433987, 2023). "SMARCA4 dysregulation is associated with tumor mutation burden (TMB), mismatch repair (MMR), microsatellite instability (MSI) and DNA methylation." (PMID 37217462, 2023). "Two of the three unrelated SCCOHT index patients carried germline PVs in the SMARCA4 gene (patients #1 and #2), and complementary genetic tumor analyses suggested a loss of the SMARCA4 wildtype alleles." (PMID 37345881, 2023). "In summary, a structure-guided exit vector hop enabled discovery of small molecule degraders that form higher affinity complexes, enabling demonstration of prolonged biomarker modulation and anti-tumour efficacy in vivo in a SMARCA4-deficient xenograft model." (PMID 36216795, 2022). "As SMARCA4 expression is negatively associated with CD8 + T cell infiltration of tumours, it has been suggested to control the magnitude and duration of inflammation." (PMID 35218417, 2022). "This also included one case with a SMARCA4 loss of function mutation in tumor-free normal tissue, potentially representing a germline or mosaic mutation." (PMID 36443295, 2022). "SMARCA4-UT is characterized by inactivating mutations of SMARCA4, a suppressor tumor gene, resulting in loss of expression of brahma-related gene (BRG1)." (PMID 35326552, 2022). "The CGP demonstrated the inactivating of SMARCA4 alterations and a low tumor mutational burden (TMB) in 94% of SCCOHT cases." (PMID 35200537, 2022). "Thoracic SMARCA4-deficient undifferentiated tumors are a new type of neoplasm that commonly occur in the mediastinum, progress rapidly, and show a poorer prognosis." (PMID 35778998, 2022).